ENSG00000267706 (novel transcript)
Gene: Protein-coding gene on chromosome 19 (55,352,301 to 55,359,516, reverse strand). Ensembl gene ENSG00000267706.
Genetic constraint (gnomAD): Missense variants: 595 observed, 601.66 expected, observed/expected ratio (o/e) 0.99, 90% interval 0.92 to 1.06. Synonymous variants: 235 observed, 265.04 expected, observed/expected ratio (o/e) 0.89, 90% interval 0.8 to 0.99.